ADAMTS13 (ADAM metallopeptidase with thrombospondin type 1 motif 13)
Diseases named in the same sentence as ADAMTS13 in open-access papers (continued):
Sharing a sentence is not in itself a finding about the gene and the disease.
anemia (21 papers, 2012 to 2025). A reduction in the number of red blood cells, the amount of hemoglobin, and/or the volume of packed red blood cells. "Lactate dehydrogenase, haptoglobin, coagulation panel, fibrinogen, ADAMTS13 activity and inhibitor titer, complement, and urinalysis are recommended, along with the other common laboratory assessments for anemia." (PMID 32421502, 2020). "Although the pathogenetic model of TTP in both congenital and acquired cases is the diminished VWF cleavage, difficulties in the measurement of ADAMTS13 antigen and antibody, usually lead to a clinical diagnosis based on laboratory findings consistent with microangiopathitic anemia." (PMID 28791286, 2017). "Lab tests showed low platelets, anemia, high LDH, undetectable haptoglobin, high bilirubin, and very low ADAMTS13 activity with high inhibitor levels, confirming acquired TTP." (PMID 40827194, 2025). "They had more D-dimers (p = 0.005), a lower ADAMTS13 activity (p = 0.002) with higher vWF:Ag/ADAMTS13 activity ratios (p = 0.005), higher CRP levels (p < 0.001) and more anemia (p = 0.02)." (PMID 38915768, 2024). "The patient’s consciousness quickly improved, hematologic damage ameliorated, platelet count increased to 45 × 109/L, anemia improved with hemoglobin reaching 101 g/L, and reexamination showed plasma ADAMTS-13 activity level at 88.79% without any ADAMTS-13 inhibitors." (PMID 39969357, 2024). "Due to concomitant anemia and thrombocythemia (but no LDH elevation), screening for haptoglobin (elevated) and ADAMTS13 activity (elevated) was performed, and therefore, TTP and HUS could be ruled out." (PMID 40149624, 2025).
diabetes (19 papers, 2008 to 2025). "In the same study ADAMTS13 activity was furthermore associated with a higher risk of incident diabetes and suggested that ADAMTS13 has a role in the occurrence of type 2 diabetes at earlier stages–even before a rise in glucose." (PMID 36574434, 2022). "Although ADAMTS13 seems to correlate well with diabetes, high triglyceride and low high-density lipoprotein cholesterol levels, ADAMTS13 deficiency still carries an independent risk for cardiovascular events in chronic HD patients." (PMID 34819564, 2021). "A versatile role of ADAMTS13 was further suggested, when we recently showed that high activity of ADAMTS13 relates to a higher risk of diabetes in the general population." (PMID 29615758, 2018). "We investigated independent and synergistic effects of VWF and ADAMTS13, and explored these associations in the context of prior studies linking ADAMTS13 to diabetes, angiogenesis, and extracellular matrix integrity." (PMID 29615758, 2018). "Third, the association between ADAMTS13 and diabetes was first described in the same cohort as drawn from in the present analyses, and (large-scale) replication is warranted." (PMID 29615758, 2018). "If VWF is associated with diabetes through its prothrombotic function, then we would expect ADAMTS13, with its antithrombotic function, to be inversely associated with the risk of diabetes." (PMID 27787621, 2017). "High vWF have generally been associated with diabetes, but the results for ADAMTS13 are more diverging." (PMID 29200971, 2017). "ADAMTS13 activity was associated with an increased risk of incident diabetes (HR 1.17 [95% CI 1.08, 1.27]) after adjustment for known risk factors and VWF antigen levels." (PMID 27787621, 2017). "If the association with diabetes is strongest with ADAMTS13 antigen, then the association of markers of ADAMTS13 gene expression and of ADAMTS13 synthesis, secretion and degradation with diabetes should be explored." (PMID 27787621, 2017). "The association of ADAMTS13 activity with incident diabetes was strongest in the fourth quartile of VWF antigen level (HR 1.49 [95% CI 1.27, 1.75])." (PMID 27787621, 2017). "In our study, ADAMTS13 activity was associated with an increased risk of incident diabetes, even after adjustment for other known risk factors, including VWF antigen, fasting glucose and fasting insulin levels." (PMID 27787621, 2017). "ADAMTS13 activity was associated with a 19% increased risk of incident diabetes per SD in the age- and sex-adjusted model (HR 1.19 [95% CI 1.10, 1.30]), and this association remained unchanged after adjusting for potential confounders." (PMID 27787621, 2017). "In conclusion, we identified ADAMTS13 activity as a novel independent marker of incident diabetes that is associated with both diabetes and prediabetes." (PMID 27787621, 2017). "Future studies should investigate whether ADAMTS13 activity or antigen level is most strongly associated with diabetes." (PMID 27787621, 2017). "One cross-sectional study reported an association between ADAMTS13 and prevalent diabetes." (PMID 27787621, 2017). "However, the association of ADAMTS13 with diabetes itself remains unexplored." (PMID 27787621, 2017). "The mechanism underlying the association of ADAMTS13 activity with diabetes remains unclear." (PMID 27787621, 2017). "Densitometric analyses demonstrated decreased ADAMTS13 protein levels in the retina of rats after 4 weeks of STZ-induced diabetes." (PMID 39851513, 2025). "Our findings suggest that enhancing ADAMTS13 levels in situ ameliorates diabetes-induced retinal inflammation and vascular dysfunction." (PMID 39851513, 2025). "Treatment with intravitreal ADAMTS13 significantly reduced the diabetes-induced breakdown of the BRB compared with PBS-treated diabetic eyes." (PMID 39851513, 2025). "We also demonstrated that ADAMTS13 protein was significantly downregulated in the retinas of rats after four weeks of STZ-induced diabetes." (PMID 39851513, 2025).
diabetes (continued). "For instance, a prior study reported an association between elevated ADAMTS13 activity (which cleaves VWF multimers and reduces their functional activity) and increased diabetes risk." (PMID 40969184, 2025). "We study the protection against diabetes-induced retinal injury in experimental rats by supplementation with recombinant ADAMTS13." (PMID 39851513, 2025). "The intravitreal administration of ADAMTS13 attenuates diabetes-induced BRB breakdown, the downregulation of VE-cadherin and β-catenin, and the upregulation of VWF, CD41, phospho-ERK1/2, HMGB1, VCAM-1, and ICAM-1." (PMID 39851513, 2025). "In the plasma of patients with diabetes some studies have seen significantly lower concentrations of ADAMTS13 activity compared to control groups." (PMID 36574434, 2022). "ADAMTS13 activity was positively correlated with diabetes, triglyceride and hemoglobin A1c, and negatively with high-density lipoprotein cholesterol levels in HD patients." (PMID 34819564, 2021). "With a follow-up of 20.3 ± 7.3 months, the Cox proportional hazards model revealed that low ADAMTS13, comorbid diabetes, and coronary heart diseases have independent correlations with the development of cardiovascular events." (PMID 34819564, 2021). "These analyses were prompted by our recent study in which we found increased risks of diabetes with higher ADAMTS13 activity." (PMID 29615758, 2018). "While we encourage attempts for replication of our findings in other populations, we believe that current insight warrants serum glucose and diabetes history to be taken into account in future study of ADAMTS13." (PMID 29615758, 2018). "Low ADAMTS13 activity is associated with dementia risk during prolonged follow-up, with data suggesting an interactive mechanisms between ADAMTS13 and diabetes in the development of dementia." (PMID 29615758, 2018). "Cox proportional hazards models were used to examine the association of ADAMTS13 activity and VWF antigen with incident diabetes." (PMID 27787621, 2017). "As diabetic conditions in rats were associated with decreased levels of retinal expression of ADAMTS13, we hypothesized that enhancing the expression of ADAMTS13 might ameliorate diabetes-induced retinal injury." (PMID 39851513, 2025). "In conclusion, our findings suggest that therapeutic approaches to enhance ADAMTS13 levels could potentially be a promising strategy to ameliorate diabetes-induced retinal inflammation and vascular dysfunction." (PMID 39851513, 2025). "Diabetes-induced retinal inflammation could aggravate retinal damage through the reduction of retinal ADAMTS13." (PMID 39851513, 2025). "The association was modified by the presence of impaired fasting glucose or diabetes (P-interaction = 0.003), such that low activity of ADAMTS13 related to higher risk of dementia primarily in non-diabetics, but not in those with (pre-)diabetes." (PMID 29615758, 2018). "In contrast to findings for VWF antigen, low ADAMTS13 activity was associated with cognitive decline and dementia risk throughout the 15-year follow-up in individuals without (pre-)diabetes." (PMID 29615758, 2018). "First, despite rigorous adjustment for known determinants of VWF and ADAMTS13, residual confounding may still exist, in particular with respect to other factors involved in hemostasis, diabetes, or possibly angiogenesis and extracellular matrix stability." (PMID 29615758, 2018). "Our findings suggest that diabetes pathophysiology, rather than antidiabetic medication, modifies the association between ADAMTS13 and dementia risk." (PMID 29615758, 2018). "Although ADAMTS13 activity was positively associated with fasting glucose and insulin, the association with incident diabetes did not change when we adjusted for these covariates." (PMID 27787621, 2017).
diabetes (continued). "To our knowledge, the association of ADAMTS13 with diabetes has not previously been studied with diabetes used as the primary outcome, and we are the first to examine this association in a large prospective population-based cohort study." (PMID 27787621, 2017). "Increased VWF levels and lower ADAMTS13 activity in dialysis patients as compared with the general population could be a reflection of a high prevalence of comorbidities, including cardiovascular diseases and diabetes mellitus." (PMID 34134634, 2021). "ADAMTS13 was associated with more rapid decline in cognitive test performance during 15 years of follow-up, which was again most profound in individuals without diabetes." (PMID 29615758, 2018). "Additionally, low ADAMTS13 activity may contribute to the renal and cardiovascular complications of diabetes." (PMID 27787621, 2017). "Here, we determine whether ADAMTS13 activity and VWF antigen are associated with incident diabetes." (PMID 27787621, 2017). "Patients with highest quartile of VWF or lowest quartile of ADAMTS13 had an increased age, cardiovascular disease, diabetes mellitus and an increased CRP as compared with highest quartile of VWF or lowest quartile of ADAMTS13, respectively." (PMID 34134634, 2021). "There was an interaction between ADAMTS13 activity and VWF antigen level with incident diabetes (p = 0.01)." (PMID 27787621, 2017). "Plasma levels of ADAMTS-13 and von Willebrand factor (VWF) in controls amongst the different binary variables examined [i.e. according to sex, smoking, diabetes, and the taking of medication for high blood pressure (BP) or high cholesterol]." (PMID 18194418, 2008). "The prognosis of patients with AIS at 90-days after IVT was used as the dependent variable, and age, smoking, hypertension, diabetes, coronary artery disease, hyperlipidemia, atrial fibrillation, IL-6, MMP-9, ADAMTS13, TRX, TNC, and GSN were considered independent variables." (PMID 36127663, 2022). "Low ADAMTS13 activity and high VWF levels may exacerbate small vessel disease, which in turn may contribute to the development of diabetes." (PMID 27787621, 2017). "In the Rotterdam study higher ADAMTS13 activity in patients with diabetes compared to those without was reported, and they also showed ADAMTS13 activity to be an independent risk factor for both prediabetes and diabetes type 2." (PMID 29200971, 2017). "These researchers did not observe a significant difference in ADAMTS13 levels between 86 diabetes patients and 26 healthy controls." (PMID 27787621, 2017). "We previously observed that ADAMTS13 activity is 5% higher in participants with prevalent diabetes compared with those without prevalent diabetes." (PMID 27787621, 2017). "As the association between ADAMTS13 and diabetes did not appear to be explained by its cleavage of VWF, ADAMTS13 may have an independent role in the development of diabetes." (PMID 27787621, 2017).
Hypertension (19 papers, 2008 to 2026). The presence of chronic increased pressure in the systemic arterial system. "A recent study on patients with TTP who presented with neurological symptoms suggested that old age, hypertension, smoking, and high plasma concentrations of anti-ADAMTS-13 IgG may be the risk factors for developing cerebral infarction in these patients." (PMID 36709264, 2023). "Distinguishing features—including severe hypertension with retinopathy, relatively higher platelet counts, preserved ADAMTS13 activity, and characteristic smear or biopsy findings—help direct appropriate therapy." (PMID 41236470, 2026). "Further evaluation, including preserved ADAMTS13 activity and the context of severe hypertension with retinopathy, supported malignant hypertension–induced TMA, and plasma exchange was deferred." (PMID 41236470, 2026). "TMA induced by malignant hypertension mimics TTP and aHUS but typically presents with extreme hypertension, hypertensive retinopathy, relatively higher platelet counts, preserved ADAMTS13 activity, and biopsy- or smear-proven vascular changes." (PMID 41236470, 2026). "The AF group had a lower frequency of the GA genotype of ADAMTS13 rs28503257 and a higher frequency of the CT genotype of ADAMTS13 rs34054981 compared to the hypertension group." (PMID 40724958, 2025). "The distribution of genotypes for ADAMTS13 rs28503257 (p = 0.047) and rs34054981 (p = 0.013) differed between the atrial fibrillation (AF) group and the hypertension group." (PMID 40724958, 2025). "In a hypertension model, miR-3656 suppressed cell proliferation and migration of human umbilical vein endothelial cells but induced apoptosis of these cells by targeting eNOS and ADAMTS13." (PMID 35053270, 2022). "Based on their disease–gene associations, these biomarkers are involved in vascular inflammation (HO-1, LPL, PAPPA, ADAMTS13, ADM, PGF, and GDF-2), hypertension, and arterial disease (PAPPA, ADAMTS13, ADM, and PGF)." (PMID 35327515, 2022). "We recognize that factors such as pre-existing medical conditions (e.g., hypertension), long-term immunosuppressive medication use, and specific aspects of TTP itself—like ADAMTS13 activity and antibody status—could have impacted brain volume measurements." (PMID 41191615, 2025). "ADAMTS-13 was higher in those taking compared with those not taking medication for high blood pressure." (PMID 18194418, 2008). "Furthermore, ADAMTS13 activity was independently negatively correlated with the overall CSVD burden (odd ratio = 21.33; 95% CI (17.46, 54.60); p < 0.01) after adjustment for age, history of hypertension, and current smoking." (PMID 34690744, 2021).
liver disease (19 papers, 2011 to 2025). "Anti-ADAMTS13 antibodies, cancer (and cancer therapy), chronic inflammation, pregnancy, liver disease, and disseminated intravascular coagulation are all associated with acquired ADAMTS13 deficiencies." (PMID 40217615, 2025). "HSCs are the major ADAMTS13-producing cells in the liver; thus, previous studies have focused on the potential role of ADAMTS13 in the pathophysiology of liver diseases associated with sinusoidal and/or systemic microcirculatory disturbances." (PMID 35407443, 2022). "By contrast ADAMTS13 was widely studied since liver is the main source of ADAMTS13 in human and changes in ADAMTS13 activity was associated with liver disease." (PMID 33805340, 2021). "Since HSCs were shown to be the major producing cells in the liver, much attention has been paid to the potential role of ADAMTS13 in the pathophysiology of liver diseases associated with sinusoidal and/or systemic microcirculatory disturbance." (PMID 21994870, 2011). "Imbalance between ADAMTS13 and VWF is associated with portal hypertension, which induces ACLF development." (PMID 36829443, 2023). "This is the first study to focus on ADAMTS13 activity and concentration in liver diseases including SOS." (PMID 38003518, 2023). "Other studies suggested that patient selection has a relevant effect on the relation between liver disease severity, ADAMTS13-Act, and VWF multimer size." (PMID 37605068, 2023). "A Disintegrin and Metalloproteinase with a Thrombospondin Type 1 motif, member 13 (ADAMTS-13), is another factor influenced by chronic inflammation and advanced liver disease." (PMID 37443746, 2023). "Nevertheless, ADAMTS13 is significantly reduced in patients with various liver diseases such as hepatic alcoholic hepatitis, liver cirrhosis, veno-occlusive disease and patients undergoing liver transplantation." (PMID 30976044, 2019). "ADAMTS13:AC decreases with increasing severity of liver disease, leading the observed imbalance between the decreased ADAMTS13:AC and the increased VWF:Ag in cirrhotic patients." (PMID 31638892, 2019). "As a result, the Child-Pugh score and spleen volume were independently selected, indicating that ADAMTS13 : AC is closely related to the severity of liver disease and splenomegaly in cirrhotic patients." (PMID 21994870, 2011). "ADAMTS13 : ACs were significantly lower in LC patients with hepatic encephalopathy, hepatorenal syndrome, and severe esophageal varices than those without." (PMID 21994870, 2011). "While reduced ADAMTS13 levels impair processing of HMW multimers, the observed HMW multimer loss in patients with liver disease may also result from consumption due to formation of platelet-rich microthrombi in the liver or other tissues [2,]." (PMID 41035784, 2025). "Enhanced formation of neutrophil extracellular traps and oxidative stress are hallmarks of liver disease and may explain the decreased specific activity of ADAMTS13." (PMID 41035784, 2025). "Because the hemodynamic effects of portal hypertension (PHT) can induce hepatic encephalopathy, HRS, and ascites, it is possible that ADAMTS13:AC and VWF:Ag are associated with these conditions through Et-induced development of hepatic encephalopathy, HRS, ascites, and subsequent PHT." (PMID 35407443, 2022). "Monitor of ADAMTS13: AC during ETV treatment could provide utility for early prediction of progressive liver disease and may help to predict long-term HBeAg SC in patients with CHB." (PMID 30976044, 2019). "Moreover, enhanced protein arginine methylation may occur in patients with liver diseases and may therefore contribute to reduced ADAMTS13 activity." (PMID 41035784, 2025). "Since the ADAMTS-13 to VWF ratio (ADAMTS-13/VWF) and FVIII to PC ratio (FVIII/PC) are linked to alterations that occur during liver decompensation or are associated with complications related to portal hypertension, their role as predictive biomarkers has been postulated in several studies." (PMID 37443746, 2023).
liver disease (continued). "ADAMTS13 deficiency increases plasma UL-VWFM levels, which results in increased platelet aggregation and trending to platelet thrombi under high shear stress, and may cause sinusoidal microcirculatory disturbances that promote liver disease progression." (PMID 30976044, 2019). "Research has shown that patients with liver disease, especially those with autoimmune hepatitis, demonstrate decreased ADAMTS13 activity and elevated VWF levels; thus, ADAMTS13 is a reliable indicator of liver synthetic function." (PMID 40725629, 2025).